TLR2 (toll like receptor 2)
Diseases named in the same sentence as TLR2 in open-access papers (continued):
Sharing a sentence is not in itself a finding about the gene and the disease.
tumor (continued). "A study on 128 MCC patients revealed that decreased expression of TLR 9 correlated strongly with MCPyV positivity of the tumor, while expression of TLR2, 4, 5, and 7 did not correlate with the viral status of the tumor." (PMID 32635198, 2020). "In addition, activation of TLR2 by endogenous extracellular matrix-derived proteoglycan versican and TLR4 by HMGB-1 from damaged cells are known to promote tumor growth in a context-dependent manner." (PMID 32422978, 2020). "Neither TLR2 nor TLR4 immunoexpression associated with patient age, the histological type of tumor, or the Dukes tumor stage." (PMID 32424768, 2020). "Therefore, TLR2 and TLR9 signaling can synergistically induce robust CTLs and modify the tumor microenvironment toward regression." (PMID 32231003, 2020). "Elevated TLR2 and TLR4 levels were observed in lung neutrophils from tumor-bearing mice." (PMID 32943604, 2020). "In this report, we demonstrated that the DOTAP liposome could carry TLR2-fused antigens and TLR9 agonists to enhance DCs activation and reduce Tregs in the tumor microenvironment." (PMID 32231003, 2020). "Tumor-derived HMGB1 triggers a CD8+ T cell antiglioblastoma response and induces TLR2 signaling." (PMID 31240216, 2019). "To ensure that EGT combined with TLR2/6 ligand eliminated CTL suppression by TAMs, we constructed a co-culture assay system of tumor-infiltrating F4/80+ macrophages and CD8+ splenocytes to test the reversal of CTL suppression by EGT treatment and TLR2/6 ligand." (PMID 31019508, 2019). "Combination treatment of X-ray irradiation with TLR2-YAP-HIF-1α pathway inhibitors prevented tumor relapse, indicating that inhibiting the HMGB1-TLR2-YAP-HIF-1α pathway blocked radiotherapy-induced dedifferentiation of primary tumor cells and also prevents tumor relapse." (PMID 31558702, 2019). "In our whole population-based study, we retrieved 150 Finnish NPC cases and studied their tumour samples for TLR1, TLR2, TLR4, TLR5, TLR7, and TLR9 expressions by immunohistochemistry, and for the presence of EBV and high-risk HPVs with EBV RNA and HPV E6/E7 mRNA in situ hybridizations." (PMID 31238894, 2019). "Based upon the similar expression of TLR2 and AR A2a in many malignant cells of OSCC samples, co-expression of the two receptors is probably common, though may be limited to a subset of tumor cells." (PMID 29467931, 2018). "Yet, not all TLR agonists have this effect on human mMDSCs: the TLR2/1 agonist PAM3 induces them to differentiate into MACsuppress that interfere with tumor elimination." (PMID 29632539, 2018). "PSK did not inhibit tumor growth in TLR2-/- demonstrating that it is a specific TLR2 agonist and has potent antitumor effects via activation of both innate and adaptive immunity." (PMID 30018750, 2018). "The IT injection of a genetically engineered, lethal-toxin deficient strain of Clostridium novyi, that activates DCs via TLR2, can induce CD8+ T cell mediated anti-tumor effects in preclinical renal cell carcinoma, colon carcinoma, and anaplastic squamous cell carcinoma models." (PMID 30619273, 2018). "However, it was found in another study that stimulation of the monocytic cell line THP1 with tumor-exosomes induced TNF-α, IL-1β, and IL-6 through TLR2 and TLR4 signaling." (PMID 29867942, 2018). "Tumor cells can release HMGB1 into the local microenvironment, where HMGB1 binds with high affinity to several receptors, such as toll like receptor-2 (TLR-2), TLR-4, TLR-9 and advanced glycation end products (RAGE), which can lead to tumor cell survival, expansion and metastasis." (PMID 30526680, 2018). "Another recent study suggested that TLR2 may also be important for OSCC cells, because blocking TLR2 inhibited tumor growth in a xenograft immunodeficient mouse model." (PMID 29467931, 2018).
tumor (continued). "The activation via TLR2, TLR4 and TLR9 enhances IFN-γ levels, driving chemotaxis of neutrophils, DCs, and macrophages to the inoculation site, where they internalize the bacilli and/or tumor antigens, and spread through the lymphatic vessels." (PMID 29755647, 2018). "Furthermore, by down-regulating the bioactivity of TGF-β1, DCN decreases the abundance of oncogenic microRNA (miR-21), a transcriptional inhibitor of a tumour suppressor named programmed cell death protein 4 (PDCD4), in a TLR2/4 independent manner." (PMID 29435195, 2018). "Some studies demonstrated that miR-154-5p could act as a tumor suppressor gene through targeting CCND2, STAG2, E2F5, HMGA2 and TLR2." (PMID 30266084, 2018). "It has been shown that tumor-exosomes control the expansion of myeloid-derived suppressor cells through TLR2 and not TLR4, which leads to secretion of IL-6 and suppression of CD8+ T cells." (PMID 29867942, 2018). "Solute carriers may have a key role in regulating tumour angiogenesis, cell proliferation and STAT3 signalling in cancer and thus, dysregulation of these genes may also have a role in TLR2-induced pro-inflammatory mechanisms." (PMID 28225071, 2017). "Activation of TLR2 with LTA and LTA + HMGB1 resulted in significantly increased tumor cell proliferation in MIAPaCa-2 cells (120% and 123%, p < 0.05), BxPC-3 cells (117% and 132%, p < 0.0001) and PaCaDD135 cells (117% and 114%, n.s. and p < 0.005) compared to untreated cells." (PMID 27941651, 2016). "In support of this view, the tumour cells utilized in this study expressed TLR2 and TLR4, and neutralizing antibodies against these receptors indeed inhibited tumour cell migration toward biglycan, which suggested a common mechanism for biglycan to activate cell migration." (PMID 27295191, 2016). "During inflammation, cell migration and tumor metastases, HMGB1 serves as an extracellular cytokine and mediates a series of signaling molecules by binding to its membrane receptors, including RAGE, TLR4 and TLR2." (PMID 27899819, 2016). "Biglycan-treated tumour cells showed significant increases in NF-κB activity, whereas this induction was attenuated by pretreatment with TLR2 and/or TLR4 inhibitors, suggesting that biglycan-induced tumour cell migration was mediated by NF-κB activation through TLRs." (PMID 27295191, 2016). "In comparison, both Dox-TCL- and SK-TCL-pulsed DCs expressed much higher levels of expression of CD91, TLR2 and TLR4 than those detected in immature or Naive-TCL loaded DCs, suggesting specific ICD component proteins from treated tumor cells can stimulate the expression of these PRRs." (PMID 26403780, 2015). "In summary, our data show that TLR2 is a functional receptor expressed in human HNSCC that plays a direct pro-tumorigenic role, and that it can be therapeutically targeted with blocking antibodies to reduce tumor growth." (PMID 25846753, 2015). "Previous work in the lab has demonstrated the ability of hCG to enhance the secretion of versican from tumor cells, resulting in the release of these inflammatory cytokines in a TLR-2 dependent manner (data not shown)." (PMID 26608647, 2015). "Indeed, the FDA recently approved the TLR2/TLR4 agonist Bacillus Calmette-Guérin (BCG), the TLR2/TLR4 agonist monophosphoryl lipid A (MPL) and the TLR9 agonist imiquimod as anti-tumor agents." (PMID 25871398, 2015). "Replacement of the radiosensitive haematopoietic compartment with TLR-2/-4−/− or TLR-9−/− cells did not affect tumour formation, in contrast to the role of TLR-4 on haematopoietic and non-haematopoietic cells in chemically induced skin carcinogenesis." (PMID 25575023, 2015). "Particularly, PAUF binds to TLR2 and TLR4 inducing an increase in expression of AP-1 regulated genes in THP-1 cells yet does not activate the NFkB pathway, resulting in promotion of escape from innate immune surveillance and tumor growth." (PMID 26336989, 2015).
tumor (continued). "TLR-2 and TLR-4 mRNA and protein expression have been reported in thyroid cells in vitro, and these TLRs promote tumor progression in cancer by activating cell proliferation and taking part in tumor invasion." (PMID 25328756, 2014). "The co-ligation of TLR2 and TLR4 on DCs was recently shown to potentiate their immunogenicity toward a tumor, and our results suggest that this process could be inhibited by GNP10." (PMID 24802102, 2014). "Furthermore, either the TLR2 or TLR6 antibody reduced vitamin D3 signaling and tumor cell progression in vitro." (PMID 23424670, 2013). "In addition, endogenous ligands for TLRs were also identified, including HSP70 and HMGB1, which have been shown to up-regulate TLR2 and TLR4 on tumor cell surfaces and induce tumor progression and metastasis." (PMID 23650534, 2013). "However, DC/tumor-derived TGF-β1 reduces the efficacy of CTL induction, even when stimulated with combined TLR2 and TLR4 agonists in vitro." (PMID 23555011, 2013). "Using real-time PCR and immunohistochemistry analysis, we analysed TLR2 expression in 39 paired samples (tumour and adjacent noncancerous tissues from the same patient) and found that TLR2 expression is significantly up-regulated in CRC tissues (***p < 0.001)." (PMID 23866094, 2013). "Such reduction is not sufficient to affect the overall tumor growth, since we did not observed any changes in the time at which the exponential tumor growth starts, with or without TLR2 vaccination." (PMID 23734974, 2013). "Tumor cell proliferation was monitored by MTT assay and secreted cytokines in the supernatant of transfected cells were measured by bead-based FCM, the function of TLR2 siRNA was also investigated in vivo." (PMID 22815694, 2012). "TLRs (especially TLR2, TLR3, TLR4, TLR7, and TLR9) can recognize PAMPs such as LPS, LTA, and flagellin, activating NF-κB, Notch, MAPK, and STAT3 signaling pathways, leading to the recruitment and infiltration of inflammatory cytokines, and even promoting tumor development." (PMID 40102723, 2025). "Tn antigen-modified vaccines significantly inhibited tumor growth in MUC1 transgenic mice.Self-adjuvant glycopeptide vaccines (MUC1-Tn-Pam3CSK4) enhance immune responses via TLR2 agonists, inducing robust humoral and cellular immunity in tumor-bearing mice without the need for exogenous adjuvants." (PMID 40655139, 2025). "Function prediction and analysis of Actinomyces illustrated that it can induce high expression of TLR2, TLR4, and NF‐κB in young‐onset CRC and reduce infiltration of CD8+T cells in tumor microenvironment, which could provide a direction for the mechanism study of CRC induced by Actinomyces." (PMID 39234654, 2024). "Furthermore, the inhibition of TLR2 has been shown to reduce tumor growth and enhance the efficacy of doxorubicin without adversely affecting the host immune system in vivo." (PMID 38903515, 2024). "further found that in TLR2 and TLR4 agonist-stimulated monocytes/macrophages and tumor-infiltrating immune cells, tumor cells could secrete lactate to activate the IL-23/IL-17 pathway and promote tumorigenesis and growth by promoting angiogenesis and triggering a local inflammatory response." (PMID 39660139, 2024). "In particular, the expression values of TLR-2, TLR-3, TLR-4, and TLR-9 on CD3-CD56+ cells increased proportionally with the tumor stage, suggesting that these receptors may be functional as diagnostic and prognostic biomarkers in assessing the progression of GC." (PMID 39594809, 2024).
tumor (continued). "In the present study we verified that PepO acts as a TLR2/4 dual ligand agonist resulting in switching M2 macrophage to the tumoricidal M1 macrophage by activating PI3K-AKT-mTOR and inhibiting JAK2-STAT3 pathway and enhanced the anti-tumor property of the chemotherapeutic drug doxorubicin." (PMID 37925462, 2023). "We first knocked out Cd36, Tlr2, or Tlr6 in DCs by CRISPR‐Cas9 technique and found that the ASC speck formation was significantly reduced in the Cd36CRISPR‐/−, Tlr2CRISPR‐/− or Tlr6CRISPR‐/− DCs in comparison with that in wild‐type DCs after co‐culture with the Arf1‐ablated tumor cells." (PMID 37786300, 2023). "Therefore, in the current study, we investigated the amount of F. nucleatum and its relationship with the expression of inflammatory genes (TLR-2, TLR-4, TNF-α, IL-6, IL-10, IL-12β, and IL-17) and miRNAs (miR-21, and miR-31) in tumor and adjacent normal tissue of Iranian CRC patients." (PMID 38075864, 2023). "Considering the metastasis stage, TLR2 triggers the NF-κB activation to signal the induction of the proinflammatory responses and overexpression of type 1 matrix-bound metalloproteinase (MT1-MMP) in microglia thereby activating tumor-released MMP2 that promotes metastasis." (PMID 37822929, 2023). "We next explored whether the absence of either TLR2 or TLR4 affected the anti-tumor properties of PepO in vitro and in vivo." (PMID 37925462, 2023). "However, compared the TLR2−/− control group with the wildtype control group, TLR2 deficient exerted an anti-tumor effect without PepO." (PMID 37925462, 2023). "They found TLR2 expression was elevated in wounded tumor cells, and by creating an in vitro assay of wound healing, peptidoglycan (PGN), a TLR2 agonist, was revealed to accelerate the wound repair, while the dominant negative forms of TLR2 or MyD88 could significantly inhibit the process." (PMID 36588690, 2022). "In our tumor models, both TLR2 and TRL4 were expressed on ARG1+ TANs but absent on ARG1– TANs." (PMID 36377658, 2022). "The plasmid encoding pFAR4-IL-12 or TLR2 agonist alone had no impact on tumor growth compared with control mice, whereas the complete treatment consisting of pFAR4-IL-12, TLR2 lipid agonist, and HIFU limited tumor growth." (PMID 36046055, 2022). "Importantly, tumor growth inhibition was not due to the direct effects of the TLR2 agonist or GM-CSF but was instead due to the induction of antigen-specific immunity." (PMID 34599024, 2021). "To determine whether M1 or M2 macrophages play a role in tumor reduction in IL4RαKO-CAC mice, we evaluated colon M1-markers of classically activated macrophages through Toll like receptor 2 (TLR2) expression, as well as M2 markers through Programed Death Ligand 1 (PDL1) expression." (PMID 34681866, 2021). "As TLR1/2, TLR2/6, TLR4 and TLR5 are the most prominently expressed surface TLRs on NK cells, we investigated whether the co-activation of FcγRs with these TLRs would enhance the cytotoxic activity of NK cells, resulting in improved tumor cell killing." (PMID 34681717, 2021). "Importantly, activation of TLR2 only induced cytolytic activtity, but not non-cytolytic function, of peripheral and tumor-infiltrating CD8+ T cells from GC patients." (PMID 34620075, 2021). "Notably, we demonstrated a latent mechanism that exosomes could heighten the activation of the TLR2/NF-κB signalling pathway, resulting in the augment of CXCR4 expression and gathering of MDSCs into tumor microenvironment." (PMID 34659412, 2021). "However, the supernatants of these tumor cells did not activate TLR-2 or TLR-4 reporter cells, suggesting that HGMB1 (which mediates cell activation primarily via these receptors) is not dominant in regulating neutrophil trafficking to these malignant lesions." (PMID 34876407, 2021).
tumor (continued). "Thus, combination of antibody-mediated immunotherapy with TLR2 targeting could represent an opportunity to improve NK cell cytotoxicity, which is frequently impaired in HNSCC patients, resulting in enhanced anti-tumor immune responses." (PMID 34681717, 2021). "Of note, they demonstrated an additional mechanism of action of TLR2 activation, which was based on the TLR2/MyD88-mediated activation of the Wnt pathway, with the induction of the expression of its targets CD44 and Lgr5, which may lead to tumor initiation." (PMID 33321934, 2020). "In addition, we also demonstrated that lipoE7m combined with PSCpG could synergistically trigger the TLR2 and TLR9 pathways to decrease tumor immunosuppressive cells, including Tregs and MDSCs, to enhance the therapeutic effect of lipoimmunogens." (PMID 32231003, 2020). "Furthermore, different interventions were administered to the tumor metastasis model, including inhibiting HMGB1 secretion from the cytoplasm, inhibiting the function of the HMG box of HMGB1, inhibiting the activation of TLR2, or clearance of the formed NETs." (PMID 32943604, 2020). "The promoting effect of CTCs on tumor cell metastasis could be abrogated by suppressing inflammatory response with IL-37, an anti-inflammatory cytokine, or blocking CTC-derived ligands for TLR2/4." (PMID 28415700, 2017). "Additionally, DCs lacking TLR2 failed to stimulate the proliferation and activation of tumor antigen-specific T cells (especially cytotoxic T cells) after Ad treatment." (PMID 28548063, 2014). "Because TLR2 and TLR4 are expressed on the endothelium and implicated in angiogenesis independent of VEGF, biglycan might stimulate tumour angiogenesis through TLR2 and TLR4 activation." (PMID 22374465, 2012). "Accordingly, over-expression of ZEB2 and TWIST1 in surgical samples of both normal and tumor tissues can induce EMT, resulting in over-expression of representative EMT markers VIM, FN, and COLs and membrane signal transducers IL8, CXCL4, CCL5, CXCR4, PDGFRB, and TLR2." (PMID 21533028, 2011). "TLR2, TLR4, and TLR9 are expressed in primary tumors, neck metastatic tumors, and recurrent tumors of oral tongue squamous cell carcinoma (OTSCC) ranging from the tumor surface to the invasive front, which may be one of the important factors to promote the invasion of OTSCC." (PMID 39403369, 2024). "Likewise, PepO-primed TLR4−/− M2 BMDM effectively inhibited tumor cell proliferation and TLR2−/− TAM could not promote tumor cell proliferation and reverse EMT due to the lack of M2 macrophages." (PMID 37925462, 2023). "Indeed, all activators (LPS, IL-4, WGP, and tumor supernatant) upregulated Dectin-1, but not TLR-2 and TLR-4, highlighted an enhancement of Dectin-1 on the non-specific activations of macrophages, perhaps as a preparation for the possible following activations." (PMID 36142859, 2022). "Extracellular HMGB1 can also bind to TLR2 (Toll-like receptor-2), TLR4, and RAGEs, and the impediment of RAGE–HMGB1 interaction could block the activation of p44/p42, p38, and Stress-activated protein kinases (SAPK)/JNK MAP kinases, which were significantly conducive to tumor proliferation." (PMID 33466626, 2021). "Thus, inhibiting inflammatory response to reduce the production of cytokines such as G-CSF and IL-6, or blocking the ligands for TLR2/4, when the increased CTC counts is detected, might be very important for designing the therapeutic strategy to prevent tumor metastasis." (PMID 28415700, 2017). "To determine if TLR2 has a functional role in the growth of HNSCC, we first assessed whether a monoclonal antibody (α-TLR2 mAb, clone T2.5) known to block TLR2 signaling, would have any effect on these cell lines in a 3D in vitro organoid model of tumor growth." (PMID 25846753, 2015).